IL1B (interleukin 1 beta)
Diseases named in the same sentence as IL1B in open-access papers (continued):
Sharing a sentence is not in itself a finding about the gene and the disease.
autoimmune disease (258 papers, 2004 to 2026). A disorder resulting from loss of function or tissue destruction of an organ or multiple organs, arising from humoral or cellular immune responses of the individual to their own tissue constituents. "Il-1β, a key pro-inflammatory cytokine implicated in autoimmune disorders and various cellular processes 52, is primarily produced by innate immune cells and can promote the differentiation of Th17 cells." (PMID 41356191, 2026). "This dysregulation has been associated with various autoimmune diseases, in which IL-1β plays a key role in sustaining inflammation and driving tissue damage." (PMID 41009491, 2025). "In line with other autoimmune disorders, elevated NaCl concentrations have been associated with the release of pro-inflammatory cytokines such as IL-1β and IL-6 in MD." (PMID 38742115, 2024). "NLRP3 inflammasome, which is activated upon signs of cellular “danger” to trigger innate immune defense through the maturation of pro-inflammatory cytokines such as IL-1β and IL-18, is reported to be closely associated with autoimmune diseases." (PMID 35965334, 2022). "To this end, we investigated IL-1β production in pDCs from patients with plaque-type psoriasis, an autoimmune disease associated with excessive type I IFN production and pDC overactivation." (PMID 36293012, 2022). "IL-1β has been reported to be highly involved with autoimmune and autoinflammatory diseases; the pathogenesis of autoimmune disease involves genetic susceptibility." (PMID 33562074, 2021). "Abnormal production of some cytokines such as tumour necrosis factor (TNF)-α, interleukin-1-beta (IL- 1β), soluble IL-2 receptor (sIL-2R), IL-6, and chemokine IL-8 have been implicated in the pathogenesis of various inflammatory and autoimmune diseases." (PMID 34403420, 2021). "IL-1β, IL-18, and NO have been highlighted by numerous studies as essential mediators of inflammation and have been implicated in autoimmune diseases and other inflammatory conditions." (PMID 32646056, 2020). "HLA-DR is an MHC class II cell surface receptor whose increased expression had been reported to be associated with autoimmune diseases and higher production of IL-1β and IFNγ upon Toll-like receptor stimulation." (PMID 32210958, 2020). "For instance, the excessive activation of proinflammatory cytokines, including TNF-α, IL-1β, and IFNs, is associated with autoimmune diseases, such as T1DM." (PMID 32973739, 2020). "The NLRP3 inflammasome has been associated with several human inflammatory and autoimmune diseases and represents a potential therapeutic target for disrupting IL-1β production." (PMID 30894604, 2019). "Dysregulation of the IL-1 cytokine family member IL-1β or its receptor is implicated in fatigue in many autoimmune diseases." (PMID 31447842, 2019). "The pro-inflammatory cytokine interleukin-1β (IL-1β) plays important roles in immunity but is also implicated in autoimmune disease." (PMID 30761138, 2019). "A similar approach targeting IL-1β was successfully applied to treat NLRP3 inflammasome associated autoimmune diseases and cancer." (PMID 31118894, 2019). "Interleukin-1β (IL-1β) is a prominent pro-inflammatory cytokine that is implicated in a variety of autoimmune diseases and plays an important role in host defense against infections." (PMID 29932110, 2018). "Excessive inflammasome activation can promote excessive release of IL-1β and IL-18, causing autoinflammatory disorders and the subsequent development of autoimmune diseases, such as SLE." (PMID 30534157, 2018). "IL-1β, an acute-phase proinflammatory cytokine, has been implicated in the pathophysiology of several autoimmune diseases." (PMID 30622543, 2018). "Collectively, these data shed light on the enigmatic function of PTX in EAE induction and suggest that inflammatory monocytes and microbial infection can influence differentiation of pathogenic Th1/Th17 cells in autoimmune diseases through production of IL-1β." (PMID 27189410, 2016).
autoimmune disease (continued). "IL-1β is a potent pro-inflammatory cytokine associated with a wide array of inflammatory states, including some autoimmune diseases." (PMID 27242798, 2016). "IL-1β is considered a classic activator and mediator of inflammation, its deregulation has been implicated in a range of autoimmune diseases and strategies abolishing IL-1β signaling have proven efficient in treatment of many of these conditions." (PMID 26237026, 2015). "It was thus proposed that the enhanced production of IL-1β predisposes carriers to a wide spectrum of autoimmune diseases." (PMID 24137163, 2013). "However, excessive IL-1β production can lead to autoimmune diseases and cause autoinflammatory disorders." (PMID 40218416, 2025). "Mature IL-1β recruits immune cells to sites of infection; however, IL-1β overexpression is associated with various autoimmune diseases and may contribute to carcinogenesis." (PMID 40718836, 2025). "There is also evidence of a correlation between ISG expression, IL-1β and IL-18 production, and the inflammasome in patients with autoimmune disorders associated with elevated levels of IFNs such as systemic lupus erythematosus (SLE) and juvenile dermatomyositis." (PMID 38527803, 2024). "Dysregulation of IL-1β is linked to inflammatory and autoimmune diseases." (PMID 37446547, 2023). "Moreover, single nucleotide polymorphisms (SNPs) play a crucial role in autoimmune diseases, and they can affect the priming of inflammasomes, some of their components or end products (IL-1β, IL-18)." (PMID 35457026, 2022). "IL-1-β secretion promotes numerous metabolic, physiological, and inflammatory effects, and an excess of this cytokine can produce tissue damage associated with multiple inflammatory and autoimmune diseases." (PMID 34830096, 2021). "Likewise, IL-1β, which is associated with Th17 differentiation, is also involved in a number of autoimmune diseases, and neutralization of IL-1β in these autoimmune diseases can reduce disease severity." (PMID 28946890, 2017). "Moreover, in the context of autoimmune diseases such as multiple sclerosis, higher levels of vitamin D are associated with reduced disease activity and reduced levels of pro-inflammatory cytokines, including IL-1β." (PMID 39000506, 2024). "IL-17, an important proinflammatory cytokine associated with several autoimmune diseases, significantly increased in the serum of patients with GA in the early stage of acute exacerbations, positively correlated with disease activity, and also correlated with the IL-1β level in serum." (PMID 36193152, 2022). "The new role of the NLRP3 inflammasome and the mTOR pathway as regulators of IL-1β and IgM in activated B-lymphocytes studied here offers a potential new strategy to treat autoimmune disease in which IL-1β and pathogenic IgM antibodies may play a role, particularly if triggered by infectious agents." (PMID 29170665, 2017). "Pro-inflammatory cytokines such as IL-1β and IL-6 are generally associated with the stimulation of inflammation and autoimmunity, and may also stimulate production of T regulatory lymphocytes, inhibiting the development of autoimmune diseases." (PMID 29133889, 2017). "Dysregulation of IL-1β can contribute to chronic inflammatory diseases, autoimmune disorders, and other pathological conditions." (PMID 39859545, 2025). "To investigate the mechanisms underlying neutrophil activation, IL-1β release, and NET formation, we further enrolled 86 patients (4 were excluded because of systemic corticosteroid use, autoimmune disease or malignancy)." (PMID 41395250, 2025). "Monoclonal antibodies, neutralizing TNFα and IL-1β (anti-TNFα and anti-IL-1β), emerged as a significant treatment option for central nervous system (CNS) autoimmune diseases." (PMID 40338234, 2025).
autoimmune disease (continued). "The amplification of inflammation following IL-1β activation is responsible for interactions with other pro-inflammatory cytokines, such as IL-8, which enhance Th1 and Th17 responses in autoimmune diseases and exacerbate tissue damage." (PMID 41009491, 2025). "This analysis revealed the downregulation of Tnf, Il1a, and Il1b, which played important roles in triggering autoimmune diseases." (PMID 40206211, 2025). "This study explores how IL-1β signaling affects T follicular helper and regulatory cell activation in human lymphoid organs, potentially influencing autoimmune disease mechanisms." (PMID 40392614, 2025). "IL-1β is a prototypic proinflammatory cytokine that has pleiotropic effects on many cells and is important in acute and chronic inflammatory and autoimmune diseases." (PMID 39937257, 2025). "Inflammatory cytokines such as tumor necrosis factor-alpha (TNF-α), interleukin-1 beta (IL-1β), and interleukin-6 (IL-6) are elevated in many autoimmune diseases and contribute to the inflammatory milieu." (PMID 39856066, 2025). "Important roles of interleukin (IL)-1β are found in autoinflammatory disorders, but roles of IL-6 are highlighted in autoimmune diseases and PMR21." (PMID 38177227, 2024). "Interleukin-1β (IL-1β) is a therapeutic target due to its involvement in various pathological conditions, including inflammation, autoimmune diseases, and malignancies." (PMID 39092264, 2024). "Interleukin-1 beta (IL-1β) and interleukin-1 alpha (IL-1α) have potent pro-inflammatory action in infections and autoimmune diseases." (PMID 38680495, 2024). "Reports have demonstrated the therapeutic potential of blocking IL-1β in patients with acute infections and autoimmune diseases." (PMID 38400081, 2024). "Previous studies demonstrated that TLR8 is involved in inflammatory dermatosis and autoimmune diseases, which is in the upstream of NF-κB-NLRP3 and associated with the production of IL-1β, interferon (IFN)-α, and IL-645–48." (PMID 38321132, 2024). "IL-1β enhances inflammation in the course of autoimmune diseases, and also has the ability to stimulate the production of IL-6." (PMID 39456713, 2024). "Conversely, other studies have shown that MSCs decrease levels of IL-1β, IL-17α, and IL-6 while increasing IL-10 levels in various autoimmune diseases." (PMID 39273184, 2024). "Studies on the role of IL-1β in regulatory B cells were performed mainly in autoimmune diseases, in which the environment and cytokines are completely different from those in the TME." (PMID 39576827, 2024). "Uncontrolled production of IL-1β and type I IFNs is responsible for the onset of autoinflammatory and autoimmune diseases." (PMID 38527803, 2024). "Monocytes were also collected from patients with cryopyrin-associated periodic syndrome (CAPS), an inflammatory autoimmune disease, to assess the impact of OME on IL-1β secretion." (PMID 39776898, 2024). "This study and our results suggested that monocytes were the main source of IL1β signaling in autoimmune diseases." (PMID 37041166, 2023). "A low concentration of IL-1β mainly exerts an immunomodulatory effect, whereas a high concentration of IL-1β mainly stimulates the expression of inflammation and autoimmune disease-related genes, leading to fever and cachexia." (PMID 36670802, 2023). "Key cytokines like IL-6 and IL-1β emerge as central players in these changes, with potential implications for tissue repair and autoimmune disease exacerbation." (PMID 38090572, 2023). "Anti-cytokine therapy addressed against IL-1β is extensively utilized in several inflammatory and autoimmune diseases, including ocular herpetic disease." (PMID 36839481, 2023). "It constitutes anti-cytokine therapy aimed against IL-1β and is extensively applied in numerous inflammatory and autoimmune diseases." (PMID 36839481, 2023).
autoimmune disease (continued). "Recent studies have demonstrated a strong link between NLRP3/caspase-1/IL-1β axis and some autoimmune diseases including multiple sclerosis, systemic lupus erythematosus and ulcerative colitis." (PMID 35965334, 2022). "IL-33/ST2 signaling has been found to upregulate CD11b, TLR4, caspase-1, and IL-1β in a number of human and animal studies of infection and autoimmune disease." (PMID 36741845, 2022). "Many chronic diseases, such as cardiovascular diseases, cancer, and autoimmune diseases, are related to increased levels of inflammatory factors such as IL-1β, IL-6, tumor necrosis factor (TNF), and C-reactive protein (CPR)." (PMID 36062133, 2022). "As in other autoimmune diseases, inflammatory TRMs that dominate the bladder mucosal milieu have high expressions of the pro‐inflammatory cytokines including IL‐1β and TNF‐α." (PMID 35470584, 2022). "CRP plays a central role in cardiovascular disease, while IL-1β plays a key role in acute and chronic inflammatory and autoimmune diseases." (PMID 36552200, 2022). "The inflammasome NLRP3 is a multiprotein complex that regulates caspase-1 activation and assists in releasing proinflammatory cytokine IL1β, one of the most characterized cytokines known to play an important role in autoimmune diseases." (PMID 35035661, 2022). "Cytokines released by the inflammasome, especially IL-1β, produce an inflammatory effect that promotes the development of most autoimmune diseases, including RA and inflammatory bowel disease." (PMID 35457026, 2022). "IL-1β is an important mediator of inflammatory responses and is upregulated in autoimmune diseases including RA." (PMID 35635065, 2022). "For example, IL-6 and IL1B were confirmed to be involved in the regulation of the inflammatory response and the development of various autoimmune diseases, including RA, and were effective targets for treatment." (PMID 36439145, 2022). "NLRP3 inflammasome promotes Th1 differentiation in RA, induced by IL-1β in a caspase-1-dependent manner, and it can also induce differentiation and polarization of Th2, Th17 and dendritic cells in other autoimmune diseases." (PMID 35457026, 2022). "We found that POTS patients had elevations of the proinflammatory cytokines IL-1β, IL-6, IL-18, and INFΥ, which have been reported in both autoinflammatory and autoimmune diseases and, potentially, are a result of abnormal NK cell function." (PMID 35269395, 2022). "Taken together, our data indicate the importance of Tpl2 in the modulation of ERK1/2 signaling involved in the IL-1β-induced development of autoimmune diseases affecting the dermal tissue, such as atopic dermatitis." (PMID 34735542, 2021). "IL-1β-mediated induction of IL-8 expression is important for the pathogenesis of autoimmune diseases; however, the intracellular singling remains to be understood." (PMID 34735542, 2021). "They represent a critical innate immune source of interleukin 1 beta (IL-1β), a potent inflammatory cytokine, whose overproduction can contribute to autoimmune disease development." (PMID 34523079, 2021). "Interleukin-1β (IL-1β) and type I interferons (IFNs) are major cytokines involved in autoinflammatory/autoimmune diseases." (PMID 34066649, 2021). "Autoimmune disorders are propelled by type I interferon, whereas autoinflammation is distinguished by elevations of inflammasome-induced IL-1β and IL-18; IL-1β and type I IFN counter-regulate one another and interfere with adaptive immune responses." (PMID 33562074, 2021). "Both IL-1β and IL-18 play crucial parts in the pathogenesis of a range of inflammatory and autoimmune diseases." (PMID 35008798, 2021). "Two pathways commonly dysregulated in autoimmune diseases and cancer are tumor necrosis factor alpha (TNFα) and interleukin 1 beta (IL-1β) signaling." (PMID 33776573, 2021).
autoimmune disease (continued). "Together, these findings increase understanding of the modulatory mechanisms controlling the Th17 response, and of IL-1β-mediated IL-1R signaling and its contribution to the pathogenesis of autoimmune diseases such as RA." (PMID 33507149, 2021). "To elucidate the mechanism of the onset of autoimmune diseases, we established a model for IL-1β-induced dermatitis and investigated MAPK signaling pathways in IL-1β-induced IL-8 expression." (PMID 34735542, 2021). "Given the data we have uncovered, as well as TNFα/IL-1β's therapeutic relevance in autoimmune diseases and cancer, it would be beneficial to examine miR-708's ability to reduce autoimmune-related inflammation and oncogenesis." (PMID 33776573, 2021). "IL-1β is a pro-inflammatory cytokine that plays a critical role in pain, chronic inflammation, and autoimmune disorders." (PMID 34564576, 2021). "IFN-γ, TNF-α and IL-1β have long been recognized as signature pro-inflammatory cytokines that play a central role in inflammation and autoimmune diseases, high levels are positively correlated with disease outbreak." (PMID 32244599, 2020). "Among them, IL-1β exhibits a strong proinflammatory characteristic and is involved in certain autoimmune diseases." (PMID 32595732, 2020). "Recently, Th17 related cytokines such as IL-1β, IL-6, IL-17, IL-21, IL-22, and IL-23 play crucial roles in the pathogenesis of many diseases, including inflammatory diseases, autoimmune diseases, and cancers." (PMID 32252668, 2020). "Based on these findings, some new treatment strategies aiming to suppress IL-1β activity, such as synthetic IL-1RA and IL-1β traps, have been developed to reverse or ameliorate autoimmune diseases." (PMID 32973739, 2020). "Some of these disrupted inflammatory mediators, like CXCL11, CXCL20, IL-6, IL-1β, are involved in the pathogenesis of autoimmune disorders and play a potential role in tumor progression and metastasis." (PMID 31200452, 2019). "We next examined protein expression of IL-1β, a key proinflammatory cytokine, which drives several autoimmune diseases." (PMID 31191514, 2019). "Gene polymorphisms of IL-1α, IL-1β, IL-8, and TNF-α cytokines have substantially been studied in several autoimmune diseases." (PMID 31001258, 2019). "Multiple sclerosis (MS) is a disabling demyelinating autoimmune disorder of the central nervous system (CNS) which is driven by IL-23- and IL-1β-induced autoreactive Th17 cells that traffic to the CNS and secrete proinflammatory cytokines." (PMID 32010153, 2019). "Infections, autoimmune diseases, envenomation, and trauma induce an inflammatory response that is characterized by increasing levels of circulating cytokines (e.g., IL-1β) and lipid mediators [e.g., PGE2 and leukotrienes B4 (LTB4)]." (PMID 31057373, 2019). "IL‐1β has been taken for a contributing factor in either autoinflammatory or autoimmune diseases and the induction of fever." (PMID 31313506, 2019). "We found that mice successfully treated with AS101 or SAS, showed a significant decrease in pancreatic IL-1β, a cytokine that plays an important role in many autoimmune diseases." (PMID 31191514, 2019). "Autoimmune disease induces enhancement in cytokines such as IL-1β, TNF-α, IL-6, IL-12, IL-23, and IFN-γ, especially by T helper cells and macrophages." (PMID 31447842, 2019). "Mutations in NLRP12 that cause increased secretion of IL-1β have been described in patients with FCAS, and supports a role for NLRP12 in the onset of autoimmune diseases." (PMID 31170158, 2019). "Uncontrolled secretion of mature interleukin (IL)-1β and IL-18 is responsible for severe autoinflammatory or autoimmune disorders and various allergic diseases." (PMID 30992532, 2019). "Except for IL-1β (rs1143627), these findings are in line with observations of Iranian investigations on autoimmune diseases." (PMID 31001258, 2019).